CSN1S2BP (casein alpha s2 like B, pseudogene)
Synonyms: formerly CSN1S2B
Gene: Transcribed unitary pseudogene on chromosome 4 (70,127,554 to 70,142,553, forward strand). Ensembl gene ENSG00000310584.
Diseases named in the same sentence as CSN1S2BP in open-access papers:
CSN1S2BP is named in the same sentence as 6 diseases in open-access papers, as found by Europe PMC text mining. Sharing a sentence is not in itself a finding about the gene and the disease.
CSN1S2BP shares sentences with these, for which no sentence is quoted: Crohn disease (1 paper); medulloblastoma (1); Obesity (1); osteoporosis (1); osteosarcoma (1); schizophrenia (1).